FRAT1 (FRAT regulator of Wnt signaling pathway 1)
Diseases named in the same sentence as FRAT1 in open-access papers (continued):
Sharing a sentence is not in itself a finding about the gene and the disease.
esophageal squamous cell carcinoma (4 papers, 2009 to 2023). Esophageal squamous cell carcinoma (ESCC) is a type of esophageal carcinoma (EC) that can affect any part of the esophagus, but is usually located in the upper or middle third. "A previous study demonstrates that FRAT1 overexpression leads to aberrant activation of Wnt/β-catenin signaling in esophageal squamous cell carcinoma, and that FRAT1 can induce the expression of c-Myc which is a critical element in oncogenesis." (PMID 23613813, 2013). "FRAT1 is a regulator of the Wnt signaling pathway and is overexpressed in esophageal squamous cell carcinoma." (PMID 19497108, 2009). "In esophageal squamous cell carcinoma (ESCC), overexpression of FRAT1 is associated with increased cell proliferation and aberrant activation of the β-catenin/TCF pathway, a consequence of nuclear accumulation of β-catenin that promotes the transcriptional activity of β-catenin/TCF." (PMID 28340489, 2017).
gastric cancer (4 papers, 2020 to 2023). A primary or metastatic malignant neoplasm involving the stomach. "In gastric cancer (GC), since miR-3648 represses the WNT/β-catenin pathway via the inhibition of GSK-3-binding FRAT1/2 proto-oncogenes, its downregulation resulted in the upregulation of the WNT/β-catenin pathway, followed by the overexpression of MYC as a downstream effector." (PMID 37443779, 2023).
T-cell lymphomas (4 papers, 2013 to 2025). "FRAT1 was first identified as a protooncogene that contributes to the progression of mouse T-cell lymphomas." (PMID 25922553, 2015). "FRAT1 (frequently rearranged in advanced T-cell lymphomas) positively regulates the WNT signaling pathway and may function in tumor progression and lymphomagenesis." (PMID 40700040, 2025). "However, frequently rearranged in advanced T-cell lymphomas (FRAT1) and LTF exhibited the same pattern of expression by RT-qPCR and microarray analyses." (PMID 23324411, 2013).
colon cancer (3 papers, 2017 to 2024). "In this prior work, the effects in prostate and colon cancer cells were consistent with the role of FRAT1 in preventing the association of GSK-3β with the destruction complex, while the downregulation of PAK4 inhibited nuclear translocation of β-catenin." (PMID 38815861, 2024).
glioblastoma (3 papers, 2013 to 2024). The most malignant astrocytic tumor (WHO grade IV). "Knockdown of FRAT1 expression by RNA interference resulted in inhibition of cell proliferation, migration and invasion of human glioblastoma cells and also inhibition of proliferation and increased apoptosis of human gastric adenocarcinoma cells." (PMID 28340489, 2017). "In the present study, we demonstrated that specific RNAi-mediated knockdown of FRAT1 effectively suppressed aspects of each of these tumorigenic properties of glioblastoma U251 cells, both in vitro and in vivo." (PMID 23613813, 2013). "RNAi-mediated down-regulation of endogenous FRAT1 in human glioblastoma U251 cells resulted in suppression of cell proliferation, arrest of cell cycle, inhibition of cell migration and invasion in vitro." (PMID 23613813, 2013). "In this study, we used RNAi as a strategy to specifically knockdown FRAT1 expression in U251 glioblastoma cells to address whether RNAi-mediated inhibition of FRAT1 could regulate the biologic function of U251 cells." (PMID 23613813, 2013). "Our results highlight the potential role of FRAT1 in tumorigenesis and progression of glioblastoma." (PMID 23613813, 2013). "Moreover, we explored the role of FRAT1 in the proliferation, migration and invasion of U251 glioblastoma cells in vitro and in vivo by knocking-down FRAT1 with RNA interference (RNAi)." (PMID 23613813, 2013). "However, little is known with regard to how FRAT1 regulates β-catenin in glioblastoma and whether c-Myc may be involved." (PMID 23613813, 2013).
liver cancer (2 papers, 2020 to 2025). An epithelial or non-epithelial malignant neoplasm that arises from the liver. "Knocking out the FRAT1 gene downregulates β-catenin, cyclin D1, and c-myc expression in liver cancer cells and inhibits tumor cell proliferation by regulating the Wnt/β-catenin signaling pathway." (PMID 32201513, 2020). "Similarly, Fan's group 46 reported that hypoxia significantly induces overexpression of FRAT1 gene in liver cancer tissues." (PMID 32201513, 2020). "Further investigations have shown that SW inhibited HepG2 and Huh7 liver cancer cell proliferation, migration, and invasion by downregulating frequently rearranged in advanced T-cell lymphomas 1 (FRAT1) and partially suppressing the FRAT1/Wnt/β-catenin signaling axis." (PMID 40801607, 2025).
malignant glioma (2 papers, 2015 to 2020). A grade III or grade IV glioma arising from the central nervous system. "According to our previous work 24, the expression of FRAT1 was increased in human malignant glioma cell lines U251, U87 and SHG44 compared with the normal human brain cells, and in this research we chose U251 whose expression level of FRAT1 was the highest to establish in-vitro cell model." (PMID 32201513, 2020).
meningioma (2 papers, 2017 to 2021). A generally slow growing tumor attached to the dura mater. "The exhibited nuclear accumulation of β-catenin in higher-grade meningiomas may be, in part, due to loss of translational repression of FRAT1 due to the decreased levels of miR-34a-3p." (PMID 28340489, 2017). "Taken together, we were able to validate three new direct targets for miR-34a-3p, SMAD4, FRAT1 and BCL2, which are likely to be implicated in the deregulation of signaling pathways that are already known to be involved in meningioma genesis and progression." (PMID 28340489, 2017). "In meningioma cells, overexpression of miR-34a-3p resulted in decreased protein levels of SMAD4, FRAT1 and BCL2, while inhibition of miR-34a-3p led to increased levels of these proteins as confirmed by Western blotting." (PMID 28340489, 2017). "We show that SMAD4, FRAT1 and BCL2 are direct targets of miR-34a-3p and that deregulation of miR-34a-3p alters proliferation and apoptosis of meningioma cells in vitro." (PMID 28340489, 2017). "Our findings support the idea that increased miR-34a-3p levels may contribute to a decreased cellular proliferation of meningioma cells in vitro via reduced SMAD4 and FRAT1 levels." (PMID 28340489, 2017). "To date, there is no knowledge about the role of FRAT1 in meningiomas." (PMID 28340489, 2017). "The hypothesized effects of downregulation of SMAD4 and FRAT1 on proliferation and upregulation of BCL2 on apoptosis of meningioma cells and the link to deregulation of miR-34a-3p should be explored further, also in malignant meningioma cell lines." (PMID 28340489, 2017).
ovarian serous adenocarcinoma (2 papers, 2006 to 2020). An adenocarcinoma that arises from the ovary and is characterized by the presence of malignant epithelial cells that, in well differentiated tumors, resemble the epithelium of the fallopian tube or, in poorly differentiated tumors, show anaplastic features and marked nuclear atypia. "A significant association was observed in ovarian serous adenocarcinomas between FRAT1 and β-catenin expression (P<0.01)." (PMID 16479254, 2006). "We report the expression pattern of FRAT1 in some normal human tissues and that overexpression of FRAT1 in ovarian serous adenocarcinomas is significantly associated with cytoplasmic/nuclear accumulation of β-catenin." (PMID 16479254, 2006). "In total, 46% (19 out of 41) of all ovarian serous adenocarcinomas were positive for FRAT1 expression, followed by four out of 11 clear cell, four out of five endometrioid and one out of three mucinous adenocarcinomas." (PMID 16479254, 2006). "The mechanism behind the overexpression of FRAT1 in ovarian serous adenocarcinomas and its significance is yet to be investigated." (PMID 16479254, 2006). "In 41 ovarian serous adenocarcinoma tissues examined, there was a significant correlation between FRAT1 and β-catenin expression, as determined by the Spearman rank correlation test (P<0.01)." (PMID 16479254, 2006). "Wnt/ß-catenin signalling may be aberrantly activated through Frat1 overexpression in ovarian serous adenocarcinomas." (PMID 32212785, 2020). "A total of 46% of ovarian serous adenocarcinomas were positive for FRAT1 expression." (PMID 16479254, 2006). "Wnt/β-catenin signalling may be aberrantly activated through FRAT1 overexpression in ovarian serous adenocarcinomas." (PMID 16479254, 2006). "Thus, a strong correlation between expression of FRAT1 and the subcellular localisation of β-catenin indicates that FRAT1 may modulate the Wnt/β-catenin pathway in ovarian serous adenocarcinomas." (PMID 16479254, 2006).
lymph node metastasis (1 paper, 2017). "In non-small cell lung cancer (NSCLC) expression of FRAT1 correlates with β-catenin expression and is associated with tumor differentiation, tumor stage and lymph node metastasis." (PMID 28340489, 2017).
mucinous adenocarcinoma (1 paper, 2006). An invasive adenocarcinoma composed of malignant glandular cells which contain intracytoplasmic mucin. "In conclusion, FRAT1 mRNA and β-catenin protein expression were studied in 60 ovarian adenocarcinomas, including 41 serous, 11 clear cell, five endometrioid and three mucinous adenocarcinomas." (PMID 16479254, 2006).
ovarian adenocarcinoma (1 paper, 2006). An adenocarcinoma that arises from the ovary. "FRAT1 was found in 28 of 60 (46%) ovarian adenocarcinomas investigated." (PMID 16479254, 2006). "Expression of FRAT1 was found in some human normal tissues and 47% of ovarian adenocarcinomas." (PMID 16479254, 2006).
prostate adenocarcinoma (1 paper, 2023). "Notably, FRAT1 was exclusively expressed in the nuclei of normal prostate basal cells, while nuclear FRAT1 was observed in 68% (40 out of 59) of prostate adenocarcinoma samples." (PMID 38136890, 2023).
tumor (10 papers, 2006 to 2025). "We demonstrated previously that FRAT1 expression is associated with pathologic tumor grade and proliferation, as assessed by Ki-67 staining." (PMID 25922553, 2015). "In particular, Frat1 mainly functions as a positive regulator of Wnt signaling and regulates tumor progression." (PMID 36835463, 2023). "To address the functional consequences of FRAT1 cooperating with FRAT2 on tumour metastasis, we inoculated MKN45 cells transduced with Lv-vector, Lv-FRAT1, Lv-shRNA, Lv-FRAT2 shRNA2, or Lv-FRAT1 + FRAT2 shRNA2 into BALB/c-nu/nu mice." (PMID 36153370, 2022). "It would be more appropriate to utlize additional cell lines such as U87 and other tumor cell lines to evaluate the effect of FRAT1 on GSCs proliferation, colony formation, sphere formation in vitro and tumorigenesity in vivo." (PMID 32201513, 2020). "The tissue microarrays containing various normal tissues and tumour tissues were hybridised with human DIG-labelled FRAT1 probes." (PMID 16479254, 2006). "Fourth, FRAT1 synergises with FRAT2 to promote tumour metastasis in vitro and in vivo." (PMID 36153370, 2022). "To determine whether FRAT1 expression may have prognostic value, we compared the prognosis of the 23 GBM patients in our study according to the FRAT1 status of the tumor." (PMID 25922553, 2015). "Currently, accumulating evidence demonstrates that FRAT1 plays a role in tumor progression." (PMID 23613813, 2013). "In addition, staining results confirmed that FRAT1 expression was much weaker in transplanted tumor specimens derived from U251-S cells compared with the expression level of the other three groups, as assessed by immunohistochemical analysis." (PMID 23613813, 2013). "Moreover, FRAT1 depletion significantly impaired tumor xenograft growth in nude mice." (PMID 23613813, 2013). "FRAT1 and FRAT2 are tumor promoting genes whereas VANGL1 is a tumor suppressor gene which involved in the Wnt/ß-catenin signaling pathway and thus posses as a molecular target of nobiletin." (PMID 32212785, 2020). "The positive expression rate of FRAT1 was 58.82% (40/68), and the mean FRAT1 IRS was 4.25 ± 3.86 for the 68 tumor specimens; however, 5 normal brain tissue specimens had exceedingly weak or absent immunoreactivity for this protein." (PMID 25922553, 2015). "More importantly, in most cases, β-catenin accumulation was correlated with high levels of FRAT1 expression in tumour specimens, whereas tumour tissues showing no accumulation of β-catenin generally contained relatively low levels of FRAT1." (PMID 16479254, 2006).
cancer (9 papers, 2013 to 2025). A tumor composed of atypical neoplastic, often pleomorphic cells that invade other tissues. "FRAT1 and FRAT2 are important effectors of some miRNAs in human cancers; therefore, there is a need to further explore the biological effects of miR-3648 on FRAT1 and FRAT2." (PMID 36153370, 2022). "The FRAT1 and FRAT2 genes, which are cancer-associated genes, are clustered in the human chromosome at the 10q24 locus." (PMID 36153370, 2022). "This modulation of miR-490-3p has been proved in cancer development, and activation of FRAT1 contributes to several solid-tumor progression." (PMID 34319909, 2021). "Previous reports showed that FRAT1 or FRAT2 is related to cancer cell invasion and motility." (PMID 36153370, 2022). "FRAT1 is a positive regulator of Wnt signaling, and represents a potential HCC therapeutic target due to its ability to promote hypoxia-induced HCC cancer progression and metastasis." (PMID 40424447, 2025). "Most patients exhibited lower miR-3648 levels but higher FRAT1 and FRAT2 protein levels in cancer tissues (T) compared to normal gastric mucosa (N)." (PMID 36153370, 2022). "Among the genes positively associated with DANCR, we noted FRAT1 and FRAT2, which are positive regulator of the Wnt/β-catenin signaling pathway and have oncogenic roles in several cancers." (PMID 32123519, 2020). "Regardless of the cancer types, genes such as ITGA5, SERPINE1, EIF4EBP1 are majorly associated with bad outcomes; while genes such as ALDH2, DBP, FRAT1, PDCD4 are associated with good outcomes." (PMID 35197510, 2022).
FRAT1 also shares sentences with these, for which no sentence is quoted: breast carcinoma (3 papers); leukemia (3); esophageal cancer (2); astrocytoma (1); gastric adenocarcinoma (1); ovarian tumour (1); pancreatic cancer (1).